TNF (tumor necrosis factor)
Diseases named in the same sentence as TNF in open-access papers (continued):
Sharing a sentence is not in itself a finding about the gene and the disease.
Parkinson disease (306 papers, 2006 to 2026). A progressive degenerative disorder of the central nervous system characterized by loss of dopamine producing neurons in the substantia nigra and the presence of Lewy bodies in the substantia nigra and locus coeruleus. "In Parkinson’s disease, hypomethylation of the tumor necrosis factor alpha (TNF-α) promoter in the substantia nigra has been linked to increased inflammatory signaling and disease progression." (PMID 40867210, 2025). "KEGG pathway analysis demonstrated that the candidate targets were primarily enriched in inflammation-related signaling pathways, including MAPK, TNF, IL-17, Toll-like receptor, NF-κB pathways, as well as pathways associated with Parkinson’s disease." (PMID 41582997, 2025). "One clinical retrospective cohort study reported that early exposure to anti-TNFα therapy was associated with substantially reduced Parkinson’s disease incidence." (PMID 40338234, 2025). "TNF-α is a cytokine that plays an essential role in systemic inflammation and has been associated with disorders including Alzheimer’s and Parkinson’s." (PMID 36817151, 2023). "In line with earlier research, we showed a strong association between serum levels of TNF-α and Parkinson’s disease and, more specifically, with the severity of the disorder." (PMID 36613708, 2022). "Increased TNF is associated with Alzheimer's and Parkinson's disease and disruption of TNF and its receptor is protective to dopaminergic neurons in Parkinson's disease." (PMID 31770590, 2020). "At the same time, the abnormal immune response can lead to inflammation during progression of Parkinson's disease, which is associated with increased levels of inflammation factors, such as IL-13, TNF-α, and IFN-γ." (PMID 32318067, 2020). "The only cytokine that we found to be decreased in patients with MCI was TNF-alpha, which was also associated with worsening cognition and parkinsonism." (PMID 29248892, 2018). "Tear fluid was used as a potential biomarker source in a study of neuroinflammation in Parkinson’s disease; a neurodegenerative condition associated with inflammation, and increased TNF-α levels were found in tears of PD patients." (PMID 27327445, 2016). "IL-6 and TNF-α have also been shown to play a role in the neuroinflammation associated with Parkinson's disease." (PMID 25478286, 2014). "The role of chronic inflammation is substantiated by a growing body of evidence in Parkinson's disease, where raised inflammatory markers, such as interleukin-6 and tumor necrosis factor-alpha, have been observed in association with greater severity of fatigue." (PMID 40276401, 2025). "Indeed, diseases such as Alzheimer’s and Parkinson’s have been associated with heightened microglial activation, astrogliosis, and increased expression of TNFα, IL-1β, and IL-6." (PMID 39376599, 2024). "The uptake of EVMetS by C6 cells induced a strong increase in GFAP and TNF-α mRNA expression, suggesting that EVMetS promote astroglial pro-inflammatory responses, an event that has been extensively associated with the progression of Parkinson’s disease." (PMID 38136165, 2023). "Supporting the autoimmune hypothesis, these analyses including 117,773 participants showed that use of methotrexate or TNF-α inhibitors was associated with reduced risk of Alzheimer’s and Parkinson’s disease." (PMID 37118290, 2022). "TNFα is an important regulator of developmental apoptosis and synaptogenesis, but it is also implicated in the pathogenesis of neurodegenerative conditions such as Parkinson disease." (PMID 33482100, 2021). "Several pro-inflammatory cytokines, including IL-1β, IL-6, IL-8 and TNF-α have been implicated in neuroinflammation in a variety of neurodegenerative diseases including Alzheimer’s disease, Parkinson’s disease (PD), multiple sclerosis and HIV-associated neurocognitive disorders (HAND)." (PMID 25539898, 2014).
Parkinson disease (continued). "For example, in Parkinson’s disease, in which TNF-α plays a central role in the loss of dopaminergic neurons, decreases in this cytokine could reduce neuronal toxicity and slow disease progression." (PMID 22901451, 2012). "However, chronic TNF-α treatment, mimicking Parkinson's disease associated neuroinflammation, shows detrimental effects on neural progenitor cell activity." (PMID 22892385, 2012). "Chronic inflammation is a common feature of neurodegenerative diseases of the central nervous system, such as Alzheimer's disease, Parkinson's disease (PD) and multiple sclerosis (MS), too, and TNF signaling has been implicated as an important factor for the onset of demyelinating diseases." (PMID 22110694, 2011). "Furthermore, several studies show that certain TNF-α polymorphisms in genotype or promoter sequences increase the risk for Parkinson's disease." (PMID 20478040, 2010). "Further research is expanding the role of TNFα inhibition as a therapy, as it has been shown that selectively ablating TNFα receptors can attenuate dopaminergic neurotoxicity, a major neural consequence believed to underlie the development of Parkinson's disease." (PMID 22745823, 2012). "Our finding that exposure to DEE increases TNF-α selectively in the striatum may suggest that such environmental exposures may further aggravate factors associated with neurodegenerative disorders such as Parkinson's disease." (PMID 20478040, 2010). "In a Parkinson's disease mouse model, paquinimod treatment downregulated the expression of inflammatory cytokines (IL‐6, IL‐1β and TNF‐α) and suppressed the TLR4/NF‐κB signalling pathway." (PMID 41582634, 2026). "For example, it has been demonstrated that reactive microglia, by secreting IL-1α, TNFα and C1q, induce a unique phenotype in astrocytes in neurodegenerative disorders such as Alzheimer’s and Parkinson’s disease." (PMID 39463449, 2025). "Both bisphenols affected pathways such as “PARK2/PINK1/UCHL1 in Young Onset Parkinson’s Disease”, “TNF activation of NF-kB Expression Targets”, and “Androgen Receptor/FKBP5 Signaling”." (PMID 41012393, 2025). "In parkinsonism animal models, blocking TNF signaling in the substantia nigra has been shown to attenuate dopaminergic neuron loss and associated behavioral deficits." (PMID 40963744, 2025). "MS of rats with Parkinson’s disease demonstrated a neuroprotective effect with reduced levels of TNF-α as well as cyclooxygenase-2T." (PMID 40014876, 2025). "Taken together, our findings suggest that carvacrol mitigated haloperidol-induced Parkinson-like symptoms, partially through the downregulation of TNF-α and NLRP3." (PMID 39910608, 2025). "KEGG Pathway enrichment analysis showed that differentially expressed genes (DEGs) in the MPTP versus CON comparison were highly enriched in pathways such as TNF signaling, cytokine-cytokine receptor interaction, and parkinson’s disease pathway." (PMID 39042624, 2024). "An increase in the appearance of proinflammatory cytokines like TNF-α and IL-6 is closely correlated with the development of Parkinson’s disease, according to prior research." (PMID 38551975, 2024). "The obtained results reinforce the existing clinical evidence that Alzheimer's and Parkinson's diseases are accompanied by an inflammatory response, with considerably higher blood levels observed for pro-inflammatory cytokines: IL-6, TNF-α and IL-1β." (PMID 39751856, 2024). "The lesion of substantia nigra in Parkinson’s disease is upregulated and produced higher levels of inflammatory factors, TNF-α, Interleukin-6, and interferon gamma." (PMID 38600296, 2024). "TNF-alpha levels are elevated in the striatum and cerebrospinal fluid of people with Parkinson’s patients." (PMID 38904783, 2024). "The expression level of TNFα is itself a factor that correlates with the severity of neurological symptoms in patients with Parkinson’s disease." (PMID 38642286, 2024).
Parkinson disease (continued). "Differentially expressed genes in the comparison between MPTP_BFT and MPTP were shown to be enriched in parkinson’s disease, dopamine synapse, TNF signaling, and other pathways." (PMID 39042624, 2024). "The Verrucomicrobiaceae family, a constituent of the Verrucomicrobia phylum, has exhibited a notable increase and was related to elevated levels of TNFα and interferon γ in the plasma of individuals diagnosed with Parkinson’s disease." (PMID 38533501, 2024). "The overproduction of inflammatory mediators (such as TNF-α, IL-1β and NO) by microglial cells is involved in the neurodegenerative AD and Parkinson’s disease (PD), as they can damage neurons." (PMID 39376605, 2024). "When peripheral monocytes from healthy elderly subjects are exposed to TNF-alpha, tyrosine hydroxylase level increases as observed in monocytes from people with Parkinson’s disease." (PMID 38904783, 2024). "They conclude that the activation of microglia is responsible for increased levels of TNF-alpha, as observed in Alzheimer’s and Parkinson’s disease, which lead to excessive oxidative stress and result in necrosis and apoptosis." (PMID 38720902, 2024). "Several convergent mechanisms exist in Alzheimer’s and Parkinson’s disease, including the p38 pathway activation that enhances the production of proinflammatory cytokines such as IL-1beta and TNF-alpha." (PMID 38720902, 2024). "According to research, Parkinson’s patients had significantly higher quantities of TNF-α, a glial cell-related cytokine, in their brains and cerebrospinal fluid." (PMID 37936189, 2023). "Verbascoside was found to activate Nrf2 also in TNFα-treated A549 lung cells, in the neuronal tissue of a zebrafish model of Parkinson’s disease, in UV-treated HaCaT keratinocytes and in retinal pigment epithelial cells exposed to high glucose." (PMID 37894956, 2023). "Elevated levels of the pro-inflammatory cytokines detected in the brains of Parkinson’s patients have included IFNγ, IL-1β, and TNFα." (PMID 37833807, 2023). "TNF-α, a promoter of excitotoxic injury, is upregulated or dysregulated in AD, Parkinson’s disease, and motor neuron disease." (PMID 37760836, 2023). "Animal studies of Parkinson’s disease have revealed that rTMS decreased the levels of cyclooxygenase-2 and tumor necrosis factor-α in rat substantia nigra, improved motor functions and preserved the function of dopamine neurons." (PMID 37759853, 2023). "For example, administration of naturally derived polyphenol chlorogenic acid reduced neuroinflammation by inhibiting NF-кB activation as well as diminishing IL-1β and TNF-α secretion in a MPTP-mouse model of Parkinson’s disease." (PMID 38283356, 2023). "TNF-α is known to be elevated with neurodegeneration in humans, including those with AD, motor neuron disease, or Parkinson’s disease." (PMID 37760836, 2023). "Asarone, galangin, baicalein, and a-mangostin reduced oxidative stress and pro-inflammatory cytokines, such as interleukin (IL)-1, IL-6, and tumor necrosis factor-alpha in M1-activated microglia in Parkinson’s disease." (PMID 37744008, 2023). "CONPs suppressed the neuronal inflammatory responses by lowering the high levels of IL-6 and TNF-α and hence demonstrating the effectiveness of the produced CONPs in Parkinson’s disease." (PMID 37324485, 2023). "In a mouse model of Parkinson’s disease, metformin (150 mg/kg) reduced the amount of microglia, proinflammatory cytokines (TNF-α, IL-1β, and IL-6), and inducible nitric oxide synthase (iNOS)." (PMID 37759689, 2023). "As a result, we wonder if there are any links between the levels of TNF-α and orexin in cerebrospinal fluid (CSF) in patients with Parkinson's disease and rapid eye movement sleep behavior disorder." (PMID 35250828, 2022). "Studies in Parkinson's disease have reported similar attenuation of the circulating levels of cytokines IL‐1b, IL‐6 and TNF‐a in LPS treated mice." (PMID 36426551, 2022).
Parkinson disease (continued). "TNFα and IL-1β are also increased in exosomes from patients with Parkinson’s disease, which transmit pathological effects and induce motor impairment when injected to normal mice." (PMID 35911759, 2022). "TNF-α has been shown to play a role in the pathology of Parkinson's disease and disease conversion in iRBD." (PMID 35250828, 2022). "In line with our study, subchronic administration of PQ significantly elevated the amount of TNF-α in the midbrain and induced parkinsonism in mice." (PMID 35949307, 2022). "The relationship between the increased TNFα production in B cells and the progression of Parkinson’s disease needs further investigation." (PMID 35250991, 2022). "The numbers of individuals using TNF-α inhibitors or developing Parkinson’s disease were too small for subgroup analyses." (PMID 37118290, 2022). "Mucuna pruriens administration significantly decreased glial fibrillary acidic protein (GFAP), iNOS, intercellular cell adhesion molecule (ICAM), and TNF-α inflammatory parameters in MPTP-induced Parkinson's disease (PD) animals." (PMID 36589679, 2022). "In the future, the effects of TNF-α and orexin on Parkinson's disease should be studied and discussed in a larger sample size." (PMID 35250828, 2022). "Several studies observed that physical training downregulated the expression of some pro-inflammatory cytokines (IL-1β, IL-18, TNF-α) and improved cognitive performance in different models of Alzheimer’s and Parkinson’s diseases, as well as patients." (PMID 36361978, 2022). "Biofluid studies also support the role of neuroinflammatory processes in Parkinson's disease, with elevated levels of IL-2, IL-6, and TNF-α in the serum of patients with PD." (PMID 34725564, 2021). "Injection of miR-155-5p agomir increases TNF-α, IL-1β, and IL-6 amounts in the ventral midbrain of Parkinson’s disease mice." (PMID 33692340, 2021). "In regard to human Parkinson’s disease, the Th1 cytokines IFNγ and TNF have been shown to be increased in Parkinson’s disease patient blood, while abnormal Treg responses from Parkinson’s disease patients are observed too." (PMID 33704423, 2021). "To evaluate the effects of long-term tumor necrosis factor (TNF) inhibition on the risk and age at onset of Parkinson disease (PD), we performed a 2-sample Mendelian randomization study using genome-wide association studies (GWAS) summary statistics." (PMID 33608417, 2021). "Recently, it was shown that activation of microglia leads to the conversion of resting astrocytes to reactive astrocytes via secretion of IL-1α, TNFα, and C1q in a variety of neurodegenerative disorders including AD and Parkinson’s disease (PD)." (PMID 33902708, 2021). "The main focus of pre-clinical studies using DN-TNFs is on treatment of neurodegenerative diseases where elevated TNF levels are found at the site of injuries, such as MS, Parkinson’s disease (PD) and spinal cord injury (SCI)." (PMID 32528961, 2020). "Our results show that chronic systemic inflammation induced sustained neuroinflammation with microglia activation, TNFα production, BBB compromise, and cell death, inducing a parkinsonism model and conferring additional susceptibility to MPTP damage." (PMID 32015787, 2020). "In the rotenone induced Parkinson's disease rat model, not only the levels of IL-6, IL-1β, and TNF-α in striatum were improved, but the level of GABA, DA, NE, and 5-HT was significantly increasing when treatment with spermidine compared with model group." (PMID 32625082, 2020). "A study of Parkinson’s disease demonstrated that overexpressed TNF can reduce the expression of tyrosine hydroxylase (TH) and that TNF is toxic to catecholaminergic neurons." (PMID 32145751, 2020). "The family Verrucomicrobiaceae belongs to the phylum Verrucomicrobia, significantly increased and has been shown to be associated with elevated plasma concentrations of tumor necrosis factor α (TNF-α) and interferon γ in patients with Parkinson’s disease." (PMID 32038574, 2019).
Parkinson disease (continued). "TNF-α is shown to induce apoptosis or necrosis in various types of cells, results have revealed a novel effect of TNF-α on DA neuron dysfunction and subsequent neuroinflammation-induced neuron degeneration in Parkinson’s disease." (PMID 30678689, 2019). "A post-mortem study showed the increased levels of TNF-α and other inflammatory mediators in the brain of Parkinson’s disease patients." (PMID 30170624, 2018). "Experiments in a 6-OHDA Parkinson's disease model support the asseveration and truly extend the knowledge that proinflammatory cytokines such as TNF-α instead of being detrimental are beneficial for neurotoxin-induced neurodegeneration." (PMID 29854828, 2018). "Elevated levels of TNFα are found in the brain and CSF of patients with Parkinson’s disease (PD) and mouse models of PD107,122." (PMID 30401897, 2018). "An early study in Parkinson disease showed a reduced TH expression in the CNS of TNF-overexpressing mice." (PMID 29941879, 2018). "It was previously reported that Nurr1 induces transrepression of TNF-α by binding to its promoter in Parkinson’s disease." (PMID 29209166, 2017). "Furthermore, PTX, by increasing the levels of DA, TH, and DAT and decreasing TNF-alpha, appears as a potential candidate to be included in clinical trials, alone or associated with other anti-inflammatory drugs, for the treatment of neurodegenerative pathologies as Parkinson's disease." (PMID 26491600, 2015). "There are multi path physiology are involved which can lead to Parkinson’s disease such as cyclooxygenase pathway, TNF-α and cholinergic action." (PMID 26306668, 2015). "Parkinson's disease induction in a mouse model was prophylaxed with a novel TNF inhibiting agent complexed with a compound in order to facilitate transport through the blood brain barrier." (PMID 26664821, 2015). "Parkinson patients display increased serum levels of TNF-α and TNF-α receptor 1 when compared to healthy control subjects, which makes an independent contribution to the pathogenesis of this illness." (PMID 25856766, 2015). "In an MPTP-induced mouse model of Parkinson disease it was shown that TNF-alpha knockout also significantly attenuated BBB dysfunction." (PMID 24852285, 2014). "The last speaker of this session, Malú Tansey (Emory University), highlighted research on the role of ceramide and sphingolipid signaling in TNF-dependent neurodegeneration in models of Parkinson's disease (PD)." (PMID 23474627, 2013). "Despite the clear involvement of certain cytokines in Parkinsonism, such as TNF-α and IFN-γ, the possibility of treating patients with cytokine inhibitors is still underdeveloped." (PMID 24278772, 2013). "Recent results obtained from chronic Parkinsonian macaque monkeys show that IFN-γ appears elevated in plasma and brain parenchyma, and similar to TNF-α, it seems to play a critical role in the long-term maintenance of the inflammatory response in Parkinsonism." (PMID 24278772, 2013). "Chronic inhibition of soluble Tumor Necrosis Factor (TNF) with dominant-negative TNF inhibitors protects DA neurons in rat models of parkinsonism, yet the molecular mechanisms and pathway(s) that mediate TNF toxicity remain(s) to be clearly identified." (PMID 22973882, 2012). "Neural stem cell culture techniques, intraventricular tumor necrosis factor (TNF)-α infusion and the 6-hydroxydopamine mouse model were used to investigate the influence of neuroinflammation on adult neurogenesis in the Parkinson's disease background." (PMID 22892385, 2012). "For example, in Parkinson's disease (PD), significant increases in the expression of TNF-α and its receptors have been reported in the caudate and putamen of postmortem brain samples from patients with PD." (PMID 21194439, 2010). "TNF-α levels are increased in the striatum and cerebrospinal fluid of Parkinson's disease patients when compared to controls." (PMID 20478040, 2010).